TKTL1 (transketolase like 1)
Diseases named in the same sentence as TKTL1 in open-access papers (continued):
Sharing a sentence is not in itself a finding about the gene and the disease.
tumor (continued). "In the tumor tissue of KIRC patients, we discovered a notable association between PPARA and TKTL1 expression, which is a part of the peroxisome proliferator-activated receptor." (PMID 38675412, 2024). "Thiamine metabolism has been identified as a tumor-specific radiosensitizing pathway, and recent preclinical studies also indicate a role of TKTL1 in the acquisition of radioresistance." (PMID 39444815, 2024). "The correlation observed between TKTL1 and the marker genes of immune cells underscores the potential role of TKTL1 in modulating tumor immunology in these cancers." (PMID 38675412, 2024). "In KICH, KIRC, and KIRP, the tumor tissue exhibited a notably reduced expression level of TKTL1 in comparison to the surrounding normal tissues." (PMID 38675412, 2024). "EDIM detection of TKTL1 and Apo10 has recently been presented as a sensitive and specific method for several tumours in adults." (PMID 35864157, 2022). "Recent studies have shown that TKTL1 plays an important role in the development and progression of human tumours, and has been detected and correlated with several types of cancer." (PMID 35864157, 2022). "Both RMS cell lines and tumor samples showed significantly higher expression levels of TKTL1 and DNaseX/Apo10 compared to skeletal muscle cells (SkMC)." (PMID 36009359, 2022). "In the current study, we further found that high levels of TKTL1 promoted the escape of tumor cells from apoptosis induced by DOC, mediated by abnormal chromosome segregation and DNA aneuploidy." (PMID 36175412, 2022). "Tumour epitopes transketolase-like 1 (TKTL1), Apo10 (DNaseX) and GD2 were assessed: expression levels in seven NB tumour samples and five NB cell lines were analysed using RT-PCR and flow cytometry." (PMID 35864157, 2022). "Transketolase-like 1 (TKTL1) is elevated in a variety of different tumour entities and has been correlated to tumour stage, aggressive behaviour, invasive growth, therapeutic resistance, and poor prognosis." (PMID 35864157, 2022). "In the RMS samples, TKTL1 mRNA expression was the highest for tumor samples T3 and T7, which correlated with higher hypomethylation." (PMID 36009359, 2022). "We observed overexpression of TKTL1 and DNaseX/Apo10 at the mRNA and protein level in cell lines, and even higher overexpression in NB tumour specimen." (PMID 35864157, 2022). "The analysis of tumor material from patients confirmed these findings, as the expression of TKTL1 was up to 150-fold higher in RMS tumor samples compared to normal muscle tissue." (PMID 36009359, 2022). "Previous studies also discovered that the altered PPP pathway activities by the dysregulated expression of transketolase like 1 (TKTL-1) or transaldolase (TALDO) is involved in tumor growth." (PMID 35887232, 2022). "In animal level, inhibition of TKTL1 also contributed to decreased tumor volume of CC tumor bearing mice and improved histopathological status." (PMID 34922556, 2021). "The values reflect the content of tumor-derived Apo10 and TKTL1 within CD14+CD16+ monocytes in peripheral blood." (PMID 32438648, 2020). "This includes the determination of Apo10 protein epitope (Apo10) and Transketolase-like 1 (TKTL1) in monocytes, the mRNA expression level for PD-L1 on circulating tumor cells, and the Th1/Th2 ratio." (PMID 31480379, 2019). "Apo10 protein epitope characterizes tumor cells with abnormal apoptosis and abnormal proliferation while TKTL1 is a marker for anaerobic glucose metabolism, also known as Warburg effect." (PMID 31480379, 2019). "Oxythiamine, a thiamine antagonist, is able to bind TKTL1 and hinder tumor growth through inhibition of PPP and induction of cell cycle arrest." (PMID 29805774, 2018). "In summary, our results indicate a role of TKTL1 in the adaptation of tumor cells to oxygen deprivation and in the acquisition of radioresistance." (PMID 30044385, 2018).
tumor (continued). "At the same time, the sensitivity against radical and apoptosis-triggering therapies, which makes the tumor cells more resistant to radiation and chemotherapies, is reduced through the activation of the TKTL1 gene." (PMID 28425973, 2017). "The activation of the TKTL1 gene in tumor cells leads to a fermentative, oxygen-independent metabolism, which is accompanied by an increased intake of glucose and an increased formation of lactic acid." (PMID 28425973, 2017). "The malignancy of TKTL1-positive tumors is also increased because the lactic acid produced leads to an acid-based inhibition of immune cells and tumor cells that cannot be eliminated effectively by immune cells, like the killer cells." (PMID 28425973, 2017). "Compelling evidence has proved that TKTL1 is a cancer related molecule and that it plays a key role in the onset of different neoplastic disease." (PMID 28143530, 2017). "At the same time, the activation of the TKTL1 gene in tumor cells leads to increased cell proliferation and the inactivation of apoptosis, which is normally triggered by the withdrawal of growth factors and hormones." (PMID 28425973, 2017). "Nonetheless, the contribution of TKTL1 in tumor cell metabolism has been demonstrated by the finding that inhibition of TKTL1 in different tumor cells caused a significantly decrease in cell proliferation." (PMID 28553614, 2017). "This study may provide the clue, that increased antigen expression and TKTL1 expression are both a consequence of a phenotype that results from methylation changes, and it is this phenotype that associates pro-tumorigenic metabolic changes with bystander tumor antigen expression." (PMID 26907172, 2016). "TKTL1 is required for rapid growth and viability of tumor cells, and protects against apoptosis induced by growth factor withdrawal, oxidative stress, cytotoxic therapy or targeted therapies, while TKTL1 silencing hinders cancer cell proliferation." (PMID 27391434, 2016). "In vivo, silencing of TKTL1 in cancer cells reduces tumor growth, while overexpression of TKTL1 has opposite effects." (PMID 27391434, 2016). "Our observation that TKTL1 promotes invasiveness in vitro indicates that the metabolic pathways that support tumor progression are likely to be complex." (PMID 26907172, 2016). "Some of the tumor types expressing TKTL1 have responded to the transketolase inhibitor Oxythiamine that effectively blocked cell proliferation." (PMID 26907172, 2016). "Transketolase-like 1 (TKTL1) has gained increased attention due to several studies showing a TKTL1-positive staining of malignant tumor tissue of different origins and its subsequent designation as a “proto-oncogene”." (PMID 26187043, 2015). "Using immunohistochemistry, TKTL1 was found overexpressed in a variety of human cancer tissues, and a strong TKTL1 signal correlated with tumor invasiveness." (PMID 26187043, 2015). "Constitutive up-regulation of glucose metabolism by tumor cells arises as an adaption to local hypoxia and TKTL1 should enable cells to catabolize glucose in an oxygen-independent manner." (PMID 26187043, 2015). "It is required for rapid growth and viability of tumor cells and protects against apoptosis induced by growth factor withdrawal, oxidative stress, or cytotoxic therapy, while TKTL1 silencing hinders tumor cell proliferation." (PMID 25250177, 2014). "In vivo, silencing of tumor cell TKTL1 reduces tumor growth, while overexpression of TKTL1 has opposite effects." (PMID 25250177, 2014). "Multivariate analysis demonstrated Apo10 and TKTL1 expression as an independent prognostic factor for reduced tumor-specific survival." (PMID 24304513, 2013). "To analyse differences in tumor related survival dependent on TKTL1 expression in OSCC, we divided the patients in two subgroups." (PMID 24304513, 2013). "TKTL1 silencing has been shown to suppress growth and proliferation within various tumor cell lines and xenograft models." (PMID 24280319, 2013).
tumor (continued). "Applying a cut-off of more than 10% stained tumor cells measured by observer related semi-quantitative scoring (same cut-off was used for Apo10), TKTL1 expression was detected in 42% of the tumors (n = 68/161)." (PMID 24304513, 2013). "The results obtained on TKTΔ38 are discussed in light of the proposed enzymatic function of TKTL1 in tumor cell metabolism." (PMID 23118983, 2012). "Possible correlations between TKTL1 expression and tumor progression are explored, to determine its role during tumor development." (PMID 21980427, 2011). "Here we propose a new role for Ras-signaling in tumor transformation that consists of the activation by hypomethylation of different oncogenes, including TKTL1 in CRC." (PMID 21980427, 2011). "A slight tendency towards higher survivin expression in patients overexpressing TKTL1 can be regarded as a possible response of tumour cells to hypoxic conditions." (PMID 21854597, 2011). "TKTL1 protein renders tumour cells autonomous by means of infinite glucose consumption irrespective of oxygen supply." (PMID 21854597, 2011). "This is the first time that the expression of TKTL1 has been correlated with tumor staging and metastasis formation in CRC." (PMID 21980427, 2011). "Enhanced expression of Vascular-endothelial-growth-factor-receptor (VEGF-R) and Transketolase-like-1 (TKTL1) are related to hypoxic conditions in tumours." (PMID 21854597, 2011). "It has also been demonstrated that the specific inhibition of TKTL1 expression by shRNA triggers apoptosis and suppresses tumor growth." (PMID 21980427, 2011). "Our results which describe the overexpression of LDH5 in tumor cells and its correlation with TKTL1 further supports this theory of a glucose metabolism optimized for cellular growth within malignant tumors." (PMID 20385008, 2010). "The non-oxidative arm of PPP seems to be moreimportant for tumor cells based on higher expression and activity of transketolase(TKTL1) found to correlate with rate of tumor growth in some cancers including GBMs." (PMID 21317451, 2010). "As both the targeted knockdown of TKTL1 expression as well as the compound-mediated inhibition of transketolase activity exerts strong inhibition of tumour growth, TKTL1 represents an excellent candidate for a targeted treatment of aggressive carcinomas." (PMID 19812737, 2008). "We demonstrate that TKTL1 protein is expressed in invasive tumours and predicts poor patient survival in colon and urothelial cancer." (PMID 16465194, 2006). "In 16 epithelial tumour entities we tested, a subgroup of tumours was found to have upregulated TKTL1 protein." (PMID 16465194, 2006). "The correlation between tumour stage and TKTL1 protein staining intensity was 100% score 0 in pTa superficial carcinomas, 76% score 0 or 1 and 24% score 2 or 3 in pT1 tumours." (PMID 16465194, 2006). "We propose that TKTL1 upregulation in tumours leads to enhanced, oxygen-independent glucose usage and a lactate-based matrix degradation." (PMID 16465194, 2006). "Of 10 tumours initially found to be metastatic, nine showed strong overexpression of TKTL1 (grade 3)." (PMID 16465194, 2006). "Thus, the overexpression of TKTL1 provides an acidic environment for tumors to resist immune killing and enhance tumor invasion." (PMID 39644404, 2025). "However, among these members, only TKTL1 exhibits differential expression in tumor tissues when compared to normal tissues." (PMID 38675412, 2024). "This study suggests that targeting TKTL1 may reduce tumour survival and increase sensitivity to hypoxia-induced therapies." (PMID 35269752, 2022). "Furthermore, enhanced TKTL1 expression seemed to predict clinical outcomes, especially the tumor recurrence rate." (PMID 35326744, 2022).
tumor (continued). "In line with the crucial and extremely “beneficial” function of TKTL1 for tumor cell proliferation, invasive growth, and metastasis, it has already been demonstrated that TKTL1 expression is associated with poor prognosis and therapy resistance in patients suffering from different types of cancer." (PMID 36009359, 2022). "Similarly, epitope-detection in monocyte (EDIM) technologies measure circulating CD14+/CD16+ activated monocytes/macrophages with internalized tumor-derived proteins such as Apo10 and transketolase-like protein 1 (TKTL1)." (PMID 36010865, 2022). "This heterogeneity of methylation could be an indication of a mixed tumor cell population (tumor heterogeneity), as it is often observed in different tumor entities and might explain the different TKTL1 expression profiles in ARMS compared to RME." (PMID 36009359, 2022). "We inhibited the expression of TKTL1 in tumor bearing mice of CC." (PMID 34922556, 2021). "Intracellular staining of tumor-related markers such as Apo10 and TKTL1 can be considered as a methodology using the circulating CD14+CD16+ myeloid cells in the blood, which may provide information on the tumor." (PMID 32438648, 2020). "TKTL1 expression increases in CIN 2/3 or frank neoplasia stages and in neoplastic HeLa cells." (PMID 31001477, 2019). "TKTL1 enzyme reactions is involved in oxygen-independent glucose degradation and plays a crucial role in nucleic acid ribose synthesis utilizing glucose carbons in tumor cells." (PMID 31027492, 2019). "Furthermore, the activation of the TKTL1 gene in tumor cells results in an increased glucose intake and lactic acid formation, invasive growth, the formation of distant metastases and an increased relapse rate." (PMID 28425973, 2017). "Additionally, because apoptosis-triggering is inhibited by the withdrawal of growth factors, TKTL1-positive tumor cells are more resistant against anti-growth strategies e.g., anti-hormone therapies." (PMID 28425973, 2017). "The important question is whether this reflects a dependence on TKTL1 as a mechanism for tumor progression or survival." (PMID 26907172, 2016). "Our findings support this hypothesis and further contribute to clarify additional mechanisms by which TKTL1 coordinates metabolic reprogramming and tumor growth." (PMID 27391434, 2016). "So far, TKTL1 protein expression was described primarily in paraffin-embedded tumor tissue." (PMID 26187043, 2015). "TKTL1 is hypothesized to play a role in tumour response to hypoxia with increased TKTL1 expression correlating with poor patient outcome in many solid tumours." (PMID 25609015, 2015). "This is the reason why many cancer cells may show an increased expression of antioxidant proteins such as LDHA and TKTL1 as indicated by our observation, which contribute to the survival and success of the tumor." (PMID 25048361, 2014). "High expression of TKTL1 is correlated with tumor progression and poor patient prognosis." (PMID 24280319, 2013). "TKTL1 expression was used as a metabolic tumor marker indicative of invasion and adverse prognosis." (PMID 24304513, 2013). "Moreover, glucose metabolism as a "druggable" target in solid tumours is under current investigation and the potential links between high TKTL1 expression and the metastatic potential of tumours deserves further research." (PMID 21854597, 2011). "This correlation between the overexpression of TKTL1 and tumor growth, poor survival and tumor recurrence, in addition with the transcriptional upregulation of the enzyme expression caused by promoter demethylation led Smith and coworkers to suggest the enzyme as a potential proto-oncogene." (PMID 21980427, 2011). "ii) TKTL1 is necessary for tumor progression in situ and local invasiveness, but tumors that do not overexpress the enzyme are incapable of growing in its local environment and induce the metastatic behavior as a tumor survival strategy through a Darwinian selection process." (PMID 21980427, 2011).
tumor (continued). "Moreover, we show that the correlation is stronger than that between TKTL1 expression and T classification, which indicates that the effect of the enzyme increases as the tumor progresses." (PMID 21980427, 2011). "The regulation of TKTL1 expression in tumor cells is largely unexplored, but it has been proposed that it could be upregulated in response to hypomethylation." (PMID 21980427, 2011). "Therefore, we investigated LDH5 expression in non-small cell lung cancer (NSCLC), its correlation with TKTL1 and its impact on clinico-pathological parameters such as tumor stage and survival in a large and well characterized cohort of NSCLC." (PMID 20385008, 2010). "Viable tumour cells in the border zone surrounding the necrotic areas of tumours of both groups exhibited a glycolytic phenotype with expression of glucose transporter-1 and transketolase-like 1 enzyme." (PMID 18447912, 2008). "A high variability of TKTL1-expression has been described in several tumor types." (PMID 18700018, 2008). "In addition, all tumour sections of both the KD and SD groups showed a clear surface expression of Glut-1 and cytoplasmic expression of TKTL1." (PMID 18447912, 2008). "As inhibition of transketolase enzyme reactions suppresses tumour growth and metastasis, TKTL1 could be the relevant target for novel anti-transketolase cancer therapies." (PMID 16465194, 2006). "Our findings strongly indicate that overexpression of TKTL1 is responsible for the observed tumour-specific effects of transketolase enzyme reactions, and represents the basis for the observed inhibition of proliferation of cancer cells by anti-transketolase approaches." (PMID 16465194, 2006). "Why does TKTL1 overexpression correlate with tumour invasion?" (PMID 16465194, 2006). "To investigate whether elevated TKTL1, Apo10 and GD2 levels in the EDIM blood test are caused by biomarker internalisation by phagocytosis or by an upregulation that triggered in response to a tumour, we performed co-culture experiments." (PMID 35864157, 2022). "Previous studies additionally indicated that TKTL1 protein and Apo10 epitope expression levels are elevated in tumour cells and that TKTL1 may play a role as a controlling enzyme for cell cycle, glucose metabolism, invasion, metastasis and therapy resistance in tumours." (PMID 35864157, 2022). "Additionally, two patients from Groups 1 and 2 with shorter than median OS had decreasing values, while patients from Groups 1 and 2 who showed longer than median OS had mostly stable or increasing values, reflecting persistent uptake of Apo10 and TKTL1 from dying tumor cells." (PMID 32438648, 2020). "Besides their diagnostic opportunity for cancer detection, these data confirm TKTL1 as an important new target for cancer treatment allowing inhibition of tumor cell viability and the increase of sensitivity towards hypoxia-, apoptosis and reactive oxygen species inducing therapies." (PMID 24304513, 2013). "TKTL1 overexpression has been found in many different cancer types like breast, lung, renal, thyroid, ovarian, colorectal cancer, in tumors of the ocular adnexa and correlates with the increase of metastasis, poor prognosis, tumor recurrence, and resistance to chemo- and radiation therapy." (PMID 24304513, 2013). "Therefore, it is conceivable that TKTL1 significantly contributes to the elevated fermentation of glucose observed in tumours by the cleavage of Xu5P, a putatively irreversible activity which alters the concentration of this metabolite within the balanced equilibrium of sugars in the cytoplasm." (PMID 19812737, 2008). "Therefore, we investigated whether tumours that overexpress the TKTL1 protein also have activated Akt (phospho-Akt; p-Akt) indicative of an activated glucose metabolism and an inhibited β-oxidation of fatty acids." (PMID 16465194, 2006).